IL6 (interleukin 6)
Diseases named in the same sentence as IL6 in open-access papers (continued):
Sharing a sentence is not in itself a finding about the gene and the disease.
COVID-19 (continued). "The immediate goal of IL-6 antagonism is to ameliorate severe COVID-19 cases so that requirements for advanced care are minimised." (PMID 34439868, 2021). "Beyond steroids and interleukin-6, it is logical to look upstream in the canonical interleukin-1 to interleukin-6 pathway of innate immunity for additional COVID-19 treatment targets." (PMID 35919093, 2021). "IL-6, in particular, has received considerable attention as a potential biomarker of COVID-19 severity and mortality." (PMID 33232303, 2021). "The identification of IL-1β, IL-6, interferon-γ and IL-16 is an example of cytokines in the COVID-19 network." (PMID 33664395, 2021). "For example, IR HUVEC showed a significantly higher production of various inflammatory cytokines as IL6, G-CSF, and TNFα, known markers of a poor prognosis in severe infectious conditions including COVID-19." (PMID 34375950, 2021). "Some of these molecules, including IL-6, IL-12, IL-1β and IL-18, also constitute the inflammatory cytokine storm seen in severe COVID-19 cases." (PMID 33917321, 2021). "Significantly higher concentration of TNF-α (p = 0.001), IL-1β (p = 0.001), IL-6 (p = 0.001), IL-12 (p = 0.001), IL-23 (p = 0.043), and IL-33 (p = 0.001) have been found in the sera of COVID-19 patients with severe disease." (PMID 34917631, 2021). "Based on these selected cytokines, CART algorithm indicated that IL-6 was able to discriminate control and mild COVID-19 patients with an overall test accuracy of 0.92; 95% CI: (0.85, 0.97)." (PMID 34675240, 2021). "In patients with severe COVID-19, serum IL-6 levels were even reported to be increased tenfold compared with nonsevere COVID-19 patients." (PMID 34289718, 2021). "Cytokine analysis revealed that cytokines IL-6 and IL-10 were elevated in COVID-19 patients on admission and continued to increase significantly as the disease progressed, consistent with previous reports." (PMID 34307393, 2021). "In severe cases of COVID-19 inflammatory biomarkers such as IL-6 found in serum can also be present, which tend to develop because of the disease." (PMID 34356205, 2021). "We observed lower percentage of lymphocyte subpopulation, higher neutrophils to lymphocytes ratio (NLR) and higher IL-6 concentration in critical COVID-19 group than in severe group." (PMID 34064802, 2021). "It is also unclear if these associations will remain significant after accounting for therapeutic agents (e.g. dexamethasone, anti-IL-6 treatment) in COVID-19 management." (PMID 34403784, 2021). "COVID-19 patients are characterized by the presence of a dysregulated immune system, hyperinflammation, and very high IL-6 levels." (PMID 34159203, 2021). "The changes in IL-6 levels throughout the disease progression in patients with COVID-19 were analyzed." (PMID 33746945, 2021). "Our results provide a potential role for the local RAS system in regulating IL6, known to contribute to COVID-19 pathogenesis." (PMID 34248968, 2021). "Patients suffering from severe COVID-19 have been observed to show higher levels of serum proinflammatory cytokines such as interleukin (IL)-6 (IL-6), IL-1 and tumor necrosis factor (TNF)-α, also known as ‘cytokine storm’ or ‘inflammatory storm’." (PMID 33480978, 2021). "Overall, despite these methodological differences, we believe that our work is complementary to the WHO REACT study and that it confirms the potential beneficial effect of IL-6 inhibitors in patients with COVID-19 also found by the WHO REACT colleagues." (PMID 34704175, 2021). "Other IL-6 inhibitors, including sarilumab, and siltuximab, are also being studied in clinical trials for their potential outcomes in the management of COVID-19." (PMID 33714258, 2021). "Our data consolidate low serum iron, low transferrin, and high IL-6 as important predictors of disease severity in COVID-19." (PMID 34960751, 2021).
COVID-19 (continued). "By multivariable regression analysis, we found that systemic inflammatory cytokines, particularly IL-6 and SpO2, were closely associated with a reduction in GLS in COVID-19 patients." (PMID 33510459, 2021). "An elevated IL-6 is also an inflammatory signature in COVID-19 patients with acute respiratory distress syndrome (ARDS)." (PMID 34640901, 2021). "In COVID-19 patients, a pro-inflammatory status with high levels of IL-1β, IL-6 and TNF-α have been demonstrated." (PMID 34313585, 2021). "COVID-19 can result in elevated IL-6 levels, antiphospholipid antibodies, D-dimer levels, renal failure, and increased clotting issues." (PMID 34766166, 2021). "At present, several IL-6 blocking agents are being used to treat COVID-19 patients and are displaying positive outcomes by reducing disease severity." (PMID 34538093, 2021). "Subjects suffering from COVID-19 express a range of similar symptoms such as lymphopenia, hypercoagulability, and cytokine storm (elevation in IL-6, CRP, TNF, MCP1, IL-1β levels, and others)." (PMID 34680053, 2021). "In a meta-analysis of 6320 COVID-19 patients, elevated WBC count, neutrophil count, prothrombin time, D-dimer, fibrinogen, ESR, procalcitonin, IL-6, and IL-10 were all found to be associated with severe disease, ICU admission, and poor outcome in COVID-19." (PMID 34584599, 2021). "The inhibition of the IL-6/JAK/STAT pathway appears a promising therapeutic option for the alleviation of COVID-19." (PMID 34068970, 2021). "A higher amount of proinflammatory cytokines (TNF-alpha, IL-1, IL-6) and chemokines were noted in patients with severe COVID-19 findings compared to patients with mild symptoms." (PMID 33641314, 2021). "In the setting of COVID-19, the overproduction of these cytokines, especially IL-6, is responsible for the event of a cytokine storm." (PMID 34109302, 2021). "One preliminary study compared TNF-α, IL-6 and IL-8 levels in critically ill COVID-19 vs. non-COVID-19 patients." (PMID 34945111, 2021). "Despite showing a variable clinical spectrum, severe COVID-19 patients commonly exhibited shortness of breath, and production of pro-inflammatory cytokines such as IL-6, IL-8, IL-1β, IL-1RA3,56." (PMID 34413339, 2021). "BCL6 has low activity in severe and moderate COVID-19 patients; its loss implies hyper-proliferation, followed by the expression of STAT3 to secrete IL-6, contributing to the cytokine storm in severe COVID-19 patients." (PMID 34603282, 2021). "Heparin has gained increasing attention for its ability to prevent blood coagulation in COVID-19 patients affected by severe pneumonia and its concomitant anti-inflammatory effects that result in reduced IL-6 levels." (PMID 33692695, 2021). "We here retrospectively reviewed the clinical and immunological data of 18 fatal COVID-19 cases, and the results showed that these patients had severe lymphocytopenia together with high serum concentrations of inflammatory cytokines IL-6, IL-8 and IL-10." (PMID 33995382, 2021). "The development of IL-6 biosensors for COVID-19 applications requires a definite optimization of its linear operating range and LOD." (PMID 34205852, 2021). "Given the approval for RA treatment, there is potential for off-label use of these mAbs for treating severe COVID-19 where circulating IL-6 levels are high." (PMID 34835296, 2021). "SARS-CoV-2 enters the host cells via ACE-II receptor and triggers the secretion of the copious amount of IL-6;promote pulmonary fibrosis and Th2/17 programming of lungs, leading to severe lung infection in COVID-19 patients." (PMID 34659270, 2021). "The proinflammatory Th1 helper (IL-18, IP-10, MIG, and IL-10) and ARDS-associated cytokines (IL-6, MCP-1, IL-1RA, and IL-8) were increased progressively in patients with increasing severity of COVID-19." (PMID 34938289, 2021). "Evidence has suggested that cytokine storms such as higher concentrations of IL-6, IL-8 and interleukin-10 (IL-10) were related to the prognosis of COVID-19 patients." (PMID 33638944, 2021).
COVID-19 (continued). "We found a significantly higher serum concentration (p < 0.05) of TNF-α, IL-1β, IL-6, IL-12, IL-23, and IL-33 in patients with COVID-19 with severe disease." (PMID 34917631, 2021). "Patients with severe COVID-19 showed elevated levels of galectin-3, tumor necrosis factor, IL-1, and IL6, compared to those with moderate disease or normal subjects." (PMID 34205807, 2021). "The cytokine storm caused by SARS-CoV-2 infection, primarily characterised by elevated plasma concentrations of interleukin 6 (IL-6), plays a central role in COVID-19; therefore, its suppression is considered a key treatment approach in patients with COVID-19." (PMID 33011959, 2021). "In patients with cytokine storm secondary to COVID-19, elevated serum cytokine levels are mainly related to IL-1β, IL-6, CXCL10, TNF-α, IFN-γ, macrophage inflammatory protein (MIP) 1α and 1β, and VEGF." (PMID 33669011, 2021). "The importance of A1AT in fighting coronavirus infection was supported by the finding that plasma A1AT levels correlated with COVID-19 severity and with plasma IL-6 levels." (PMID 33969249, 2021). "In COVID-19, the profound viral induced inflammation, in particular IL-6 mediated, will further increase insulin resistance." (PMID 34220705, 2021). "Most COVID-19 patients with ARDS are associated with elevated levels of various cytokines, including interleukin (IL)-2, IL-6, IL-7, interferon-γ inducible protein 10 (CXCL10), granulocyte colony-stimulating factor (G-CSF), and tumor necrosis factor-α (TNF-α)." (PMID 35401158, 2021). "Cytokine profiles observed in COVID-19 patients have revealed increased levels of IL-1β, IL-2, IL-6, and TNF-α and increased NF-κB pathway activity." (PMID 33927728, 2021). "IL-6 expression in the patients with persistent signs of COVID-19 were similar to those of patients with acute COVID-19." (PMID 33941622, 2021). "COVID-19 patients that require ICU admission have higher blood concentrations of IL-6, CXCL10, CCL2 and TNF-α as compared to patients with milder disease that does not require ICU admission." (PMID 33968010, 2021). "Only two cytokines were higher in number among COVID-19 subjects than among influenza subjects (IL-6 and IL-8)." (PMID 33146673, 2021). "Two of the most promising candidate biomarkers for both COVID-19 and neurodegenerative disorders are interleukin-6 (IL6) and its receptor (IL6R)." (PMID 33339153, 2020). "In a word, IL-6 is increased in COVID-19 and AOSD and the therapy targeting it is effective, indicating a potential and potent role in the pathogenesis of cytokine storm." (PMID 33552062, 2020). "Conclusively, this retrospective study analyzed the correlation of serum IL-6 and leukocyte characteristics with the severity of COVID-19." (PMID 33329518, 2020). "Since blood IL-6 levels are highly correlated with the lethal complications of COVID-19, we propose that IL-6 plays a pivotal role in the disease augmentation and can be thus a useful biomarker for determining the disease severity." (PMID 33014208, 2020). "Most patients with severe COVID-19 exhibited significantly elevated levels of serum proinflammatory cytokines, including IL-6 and IL-1β as well as IL-2, IL-8, IL-17, G-CSF, GM-CSF, IP10, MCP1, MIP1-α (also known as CCL3), and TNF." (PMID 32984768, 2020). "The study analyzed data from 82 cases who resolved from COVID-19 and 68 cases who died from COVID-19 and reported significantly higher levels of IL-6 in mortality cases than resolving cases." (PMID 32612617, 2020). "There are indications that corticosteroids and IL-6 inhibitors, like tocilizumab, can reduce mortality and prevent mechanical ventilation in patients with COVID-19." (PMID 32982743, 2020). "Unusually high inflammatory and prothrombotic phenotype represents a striking feature of COVID-19 patients, as reflected by markedly elevated reactive protein C, fibrinogen, interleukin 6, von Willebrand factor, and factor VIII." (PMID 33488398, 2020).
COVID-19 (continued). "This is further strengthened by the recent findings of mean IL-6 levels significant lover in COVID-19 with ARDS than bacterial sepsis with ARDS51." (PMID 33303843, 2020). "IL-6 is a cytokine that is thought to increase even further the inflammation in COVID-19, thus leading to the production of more cytokines, macrophages and cytotoxic lymphocytes that increase lung inflammation." (PMID 32782493, 2020). "Interleukin-6 induced by SARS-Cov2 infection positively correlated with the severity of COVID-19 patients." (PMID 33195318, 2020). "It was recently reported that infection in COVID-19 patients with acute respiratory syndrome showed release of the pro-inflammatory cytokines like IL-1beta and IL-6." (PMID 33079950, 2020). "The administration of rhACE2 also seems to induce a reduction of IL-6 levels in severe COVID-19 patients." (PMID 33344479, 2020). "CD4+ T cells and monocytes are considered as the primary sources of high IL-6 levels in COVID-19, which in turn correlate with decreased monocytic HLA-DR expression, one of the hallmarks of the disease." (PMID 33239683, 2020). "We also observed that inflammatory markers, including elevated levels of CRP, ESR, and IL-6, were found both in patients with severe and mild COVID-19, with a significant increase detected in patients with severe COVID-19." (PMID 33163160, 2020). "TNF-α and IL-6 are important inflammatory cytokines, and we found that the levels of TNF-α and IL-6 in the plasma of patients with COVID-19 were significantly increased and positively correlated with the severity of the disease." (PMID 32976531, 2020). "The anti-inflammatory or anticoagulation therapies in the initial phase of COVID-19 should be considered in patients with a higher level of IL-6 and D-dimer or DIC, or signs of vasculitis or progressive inflammation." (PMID 33228225, 2020). "Elevated IL-6 is a typical inflammatory finding in serum of patients with acute respiratory distresses, including COVID-19." (PMID 32764275, 2020). "Another meta-analysis had also confirmed that elevated levels of IL-6 were observed in patients with COVID-19 who exhibited poor clinical outcomes." (PMID 33163160, 2020). "All COVID-19 patients had increased levels of serum IL-6, but it was 2.9-fold higher in patients with severe COVID-19." (PMID 32612615, 2020). "In this meta-analysis and systemic review, we pooled data from all available studies with acceptable quality to assess the effects of anti-IL-6/IL-6R/JAK antibodies on COVID-19." (PMID 33384605, 2020). "Among these immune system modulators, IL-6 and IL-10 showed a positive correlation with mild COVID-19 group while IL-6 showed a good correlation with severe cases." (PMID 32948238, 2020). "There are two criteria for performing plasma exchange:critical severe COVID-19 and COVID-19 that iscomplicated by liver damage and cytokine storm (highlevels of interleukin 6)." (PMID 32779447, 2020). "We then added the IL-6 gene, identified in recent publications as heavily involved in the COVID-19 progression and, interestingly, we identified several interactions with the reconstructed interactome." (PMID 32997660, 2020). "During the COVID-19 pandemic, a recent study explored the levels of cytokines, including IL-6, and the T cell frequency in three groups of individuals: healthy individuals and patients with moderate and severe COVID-19 cases." (PMID 32793246, 2020). "Patients with moderate and severe COVID-19 usually show a marked increase in their (serum) levels of IL-6, TNF-α, IL-2R, IL-10, and other inflammation-related markers such as high-sensitivity C-reactive protein, D-dimer, and ferritin." (PMID 33002109, 2020). "Most patients with severe COVID-19 exhibit enhanced levels of proinflammatory cytokines including interleukin-6 (IL-6) and IL-1β as well as MCP-1, IP-10, and granulocyte colony-stimulating factor (G-CSF) in the plasma." (PMID 32788292, 2020).
COVID-19 (continued). "Here we used IFN-β-1b which shows most of its systematic effects through IL-6 modulation to alleviate COVID-19 induced cytokine damage." (PMID 33425279, 2020). "Cox regression analysis indicated that older age and higher serum levels of interleukin-6, C-reactive protein, procalcitonin, and lactate at admission significantly predicted the progression of COVID-19." (PMID 33239109, 2020). "Peripheral blood IL-6 and leukocyte characteristics were analyzed, to evaluate the correlation with the severity of COVID-19." (PMID 33329518, 2020). "Cytokines implicated in COVID-19-associated lung injury and CRS include IL-1β, TNF-α and IL-6, which activate other proinflammatory pathways via the JAK-STAT pathway and activation of Th cells." (PMID 33059711, 2020). "In a mouse model of ARDS, which is the main cause of death in COVID-19 patients, CD26 inhibition by sitagliptin alleviated histological findings of lung injury by inhibiting the expression of IL-1β, TNF-α, and IL-6." (PMID 33269102, 2020). "The key role of IL-6 in this cascade has prompted the evaluation of IL-6 antagonists such as several specific monoclonal antibodies as tocilizumab, sarilumab and siltuximab for the treatment of severe cases of COVID-19." (PMID 33343349, 2020). "Polymorphonuclear (PMN)-MDSC expanded during COVID-19, in particular in patients who required intensive care treatments, and correlated with IL-1β, IL-6, IL-8, and TNF-α plasma levels." (PMID 33110074, 2020). "Multiple cytokines, including M-CSF (p<0.01), IP-10 (p<0.01), IL-18 (p=0.01) and IL-1RA (p<0.01) were more relevant in predicting COVID Severity Score than more frequently characterized cytokines in the context of COVID-19 such as IL-6 (p<0.01)." (PMID 33269361, 2020). "A similar anti-IL-6 agent, Sarilumab, is being investigated in clinical trials for COVID-19 (e.g. NCT04315298)." (PMID 33059711, 2020). "The increased level of IL-6 in critically ill COVID-19 patients was related to the detection of SARS-CoV-2 nucleic acid in serum." (PMID 33207753, 2020). "The purpose of the present study is to describe the distribution of baseline IL-6 levels and its kinetics among different stratifications of COVID-19 patients in Wuhan, and the outcome of compassionate use of tocilizumab." (PMID 33121497, 2020). "Tocilizumab and eculizumab are monoclonal antibodies against IL-6 and the complement protein C5 reverse the cytokine storm respectively and improve the condition of severely COVID-19 patients." (PMID 33643033, 2020). "In particular, IL-6 is thought to contribute to the progression of COVID-19 patients to severe ARDS." (PMID 32664932, 2020). "The testing of other therapeutic antibodies influencing IL-6 signalling for the treatment of COVID-19 can be expected." (PMID 33114676, 2020). "Recently, increased IL-6 production leading to lymphopenia and its reversal by tocilizumab, an IL-6 inhibitor, has been described in critically ill COVID-19 patients in need of mechanical ventilation." (PMID 33329516, 2020). "Granzyme A–expressing NK cells were negatively correlated with serum IL-6 levels in COVID-19 patients, and the impaired cytotoxic potential was restored when treated with tocilizumab." (PMID 32845937, 2020). "IL-6 increase during the cytokine storm is often correlated to COVID-19 severity, suggesting that cellular senescence and the production of SASP as a potential mechanism of SARS-CoV-2 injury to the brain." (PMID 33304309, 2020). "Regeneron Inc. also announced to enroll 400 patients in a clinical II/III trial with Sanofi, treating severe COVID-19 patients with another IL-6 inhibitor, Kevzara (NCT04359901)." (PMID 33574756, 2020). "The pivotal role of IL-6 in mediating the acute phase response seems to interest the strategical treatment in COVID-19 patients." (PMID 33160363, 2020). "A meta-analysis of 21 studies involving 3,377 patients with COVID-19 supported the notion that IL-6 was a significant indicator for the severity of COVID-19." (PMID 33384605, 2020).